C1GALT1 (core 1 synthase, glycoprotein-N-acetylgalactosamine 3-beta-galactosyltransferase 1)
Diseases named in the same sentence as C1GALT1 in open-access papers (continued):
Sharing a sentence is not in itself a finding about the gene and the disease.
tumor (continued). "C1GALT1 was upregulated in several GI and GU cancers, correlating with poor survival and elevated expression of proliferation markers like MKI67, PCNA, and MCM2–7, suggesting a role in tumor growth." (PMID 40548474, 2025). "Inhibition of C1GALT1 using a genetic or pharmacological inhibitor, such as ITZ, reduces SMO O-glycosylation, Hh signaling, and EWSR1::FLI1 expression, resulting in decreased ES cell viability and tumor growth in mice." (PMID 39894896, 2025). "The presence of C1GALT1 mRNA does not guarantee the synthesis of functional core 1 O‐glycans in tumor tissues, especially without accompanying proteomics or glycomics validation." (PMID 40548474, 2025). "Pharmacological inhibition of C1GALT1 using the FDA-approved anti-fungal drug itraconazole decreases EWSR1::FLI1 expression in human ES cell lines resulting in cell death, and suppresses ES tumor growth in xenograft mouse models." (PMID 39894896, 2025). "Several studies have highlighted the crucial role of C1GALT1‐mediated O‐glycosylation in regulating the surface localization and stability of transmembrane glycoproteins such as MUC1, CD44, and IL‐6 receptor, thereby impacting tumor growth and metastasis." (PMID 39844613, 2025). "To evaluate whether immune cells can sense the reduced IL‐6 expression in tumor cells, we treated THP‐1 and Jurkat cells with conditioned media from Mock or C1GALT1 knockout SAS cells." (PMID 37452653, 2024). "In PDAC, the deletion of glycosyltransferase Core 1 Synthase, Glycoprotein-N-Acetylgalactosamine 3-Beta-Galactosyltransferase 1 (C1GALT1) and its molecular chaperone Cosmc are both mechanisms leading to increased expression of truncated O-glycochains and increased tumor aggressiveness." (PMID 38758220, 2024). "To gain further insight into the influence of C1GalT1 change on tumour cell activities mediated by galectin-3 and MGL, we further analysed the cell surface binding receptors of galectin-3 and MGL in response to change of C1GalT expression in cancer cells." (PMID 37612278, 2023). "Here, we have found that the LGALS3 upregulation occurred in parallel to the downregulation of C1GALT1 both in vitro and in vivo in tumor tissue, with a significant negative correlation between them." (PMID 36745330, 2023). "The chicken embryo is rich of capillary network and is increasingly used as an effective in vivo model in assessing tumour growth and was used here to assess the effects of C1GalT1 expression on tumour growth without and with galectin-3." (PMID 37612278, 2023). "Tumor volume and weight in vivo were significantly reduced by ITZ treatment or C1GALT1 silencing." (PMID 35864552, 2022). "The results indicated that 85% (107/126) of PDAC tumor tissues had higher C1GALT1 levels than their corresponding non-tumor tissues (T > N)." (PMID 33420364, 2021). "Further investigation demonstrated that RAC1 expression was positively regulated by C1GALT1 in LUAD, whereas silencing Rac1 could reverse C1GALT1-induced tumor growth and metastasis." (PMID 34307388, 2021). "In addition, knocking out of C1GALT1 in PDAC cells leads to inefficient conversion of Tn antigen to T antigen, and further increases tumor progression and metastasis." (PMID 32582529, 2020). "We hypothesized that the overexpression of C1GALT1, identified as a negative indicator for patients’ prognosis in most cancer types, may alter tumor radiosensitivity in LUAD, thereby having critical consequences in cancer progression." (PMID 38662050, 2024). "Using a cut-off of 1.5-fold change, the expression levels of these four genes were down-regulated in CCA tissues compared to non-tumor tissues, evidenced by the percent of tumor cases showing high expression of C1GALT1–29% (26/90), COSMC–7% (6/90), B3GNT6–7% (15/90), and ST6GALNAC1–24% (22/90)." (PMID 35207462, 2022).
tumor (continued). "Notably, the treatment of ITZ, as one antifungal medication, could down-regulate the C1GALT1 expression, and suppress BLCA tumor growth and migratory ability in cell- and patient-derived xenografts, indicating the therapeutic potential of ITZ in BLCA." (PMID 35864552, 2022). "In OEC-M1 cells, we could not assess the effect of itraconazole in C1GALT1-knockdown cells because of no tumor growth." (PMID 29930379, 2018). "Furthermore, the ability of ITZ to suppress the growth of TC-71 or TC-32 xenografts was comparable to that observed upon knockdown of C1GALT1, and was not further exacerbated by C1GALT1 knockdown, indicating that ITZ exerts its effects on ES tumor growth by inhibiting C1GALT1." (PMID 39894896, 2025).
cancer (33 papers, 2014 to 2025). A tumor composed of atypical neoplastic, often pleomorphic cells that invade other tissues. "While previous studies have implicated C1GALT1 in cancer progression, a systematic pan‐cancer analysis exploring its gene expression patterns, epigenetic regulation, immune interactions, and prognostic significance has not been fully elucidated." (PMID 40548474, 2025). "Elevated C1GALT1 expression is associated with poorer prognoses in cancers including those of the head and neck, breast, liver, colon, ovarian, and pancreatic." (PMID 39844613, 2025). "Given the association between truncated O‐glycans and poor cancer prognosis, we screened for differentially expressed genes (DEGs) in OS and identified the elevated expression of C1GALT1 in poor survival cases and in patients with metastasis within 5 years." (PMID 39844613, 2025). "The overall survival associated with the C1GalT1 gene in various cancer types was analyzed using the Xena web portal with KM plots." (PMID 40548474, 2025). "On the other hand, the pro‐cancer effects of C1GalT1 are linked to modifications of O‐glycans on downstream targets." (PMID 40548474, 2025). "A recent study has shown that elevated C1GALT1 expression is associated with poor prognosis and contributes to cancer cell proliferation, migration, and invasion through upregulating RAC1 in LUAD." (PMID 38662050, 2024). "Bioinformatics analysis was used to explore single cell sequencing data, revealing the influence of C1GALT1 on cancer-associated cellular states." (PMID 38662050, 2024). "The present findings revealed that C1GALT1 is associated with several cancer-related cellular processes, including DNA repair, apoptosis, EMT, and G2/M checkpoint regulation." (PMID 38662050, 2024). "C1GALT1 is known to affect immune status, and mutations inC1GALT1 occur across multiple cancer types (available online)." (PMID 38807485, 2024). "In the current study, an enrichment analysis of single-cell sequencing data was performed and the cancer-associated cellular processes influenced by C1GALT1 were examined through public database." (PMID 38662050, 2024). "Core 1 synthase glycoprotein-N-acetylgalactosamine 3-β-galactosyltransferase 1 (C1GALT1) plays a key role in GalNAc-type O-glycosylation and is associated with the progression and prognosis of various types of cancer." (PMID 38807485, 2024). "Recent reports also linked high C1GALT1 expression to poor prognosis and the promotion of cancer cell proliferation, migration, and invasion through the regulation of RAC1 in LUAD." (PMID 38662050, 2024). "As the sole glycosyltransferase that catalyses the formation of Core 1-associated glycans during O-glycosylation, C1GalT1 is commonly overexpressed in various cancers such as colon, breast, gastric, head and neck cancers." (PMID 37612278, 2023). "C1GALT1 overexpression is associated with tumor growth, metastasis, and poor prognosis, and has been observed in various cancers such as ovarian, hepatocellular, breast, colorectal, and gastric cancer." (PMID 36553184, 2022). "The glycosyltransferase C1GalT1 directs a key step in protein O-glycosylation important for the expression of the cancer-associated Tn and T antigens." (PMID 35504880, 2022). "As for the C1GALT1 enzyme, it has also been implicated in cancer; however, the role is less clear-cut, with contradicting data on the pro-/antitumorogenic effect." (PMID 35784319, 2022). "The findings are consistent with studies of various cancers, in which the loss of C1GALT1 and their specific chaperones, COSMC, contribute to increased truncation of O-glycans on several mucin proteins, including MUC4 and MUC16." (PMID 35207462, 2022). "Change of C1GalT1 expression in cancer leads to alteration of O-linked carbohydrate structures on many cell membrane glycoproteins, such as mucin proteins, growth factor receptors, adhesion molecules, and death receptors." (PMID 34944925, 2021).
cancer (continued). "C1GalT1-associated TF occurrence on MUC1 on cancer cells increases cancer cell interaction with galectins and promotes cancer cell progression and metastasis." (PMID 34944925, 2021). "Change of C1GalT1 expression or activity in cancer often alters the O-linked carbohydrate structures on these cell membrane glycoproteins and changes their activity." (PMID 34944925, 2021). "C1GALT1 controls the crucial step of GalNAc-type O-glycosylation and is associated with both physiologic and pathologic conditions, including cancers." (PMID 32005975, 2020). "Targeting cancer‐associated O‐glycosylation via C1GALT1 inhibition could be an attractive strategy to enhance anti‐PD‐1 immunotherapy effects." (PMID 37452653, 2024). "Loss of C1GALT1 function is a cause of the development and progression of various cancers." (PMID 35207462, 2022). "Dysregulation of C1GALT1 has been documented in multiple cancers and is associated with aberrant core 1 O-glycosylation and cancer aggressiveness; however, the expression of C1GALT1 and its role in CCA progression remains unknown." (PMID 35207462, 2022). "In addition, C1GALT1 has also been associated with prognosis in other cancers." (PMID 36745330, 2023). "In addition, our previous studies also identified the stimulatory effect of C1GALT1-mediated O-glycosylation on RTK activity such as EPHA2, integrin, and MET in several adult cancers and C1GALT1 high expression was associated with poor survival of patients in these studies." (PMID 35169131, 2022). "Giantin is the docking site for these vesicles except those that transport C1GalT1 in normal cells and benign cancer cells under basal conditions." (PMID 39592427, 2025). "This study provides a comprehensive pan‐cancer bioinformatic analysis of C1GALT1 expression, DNA methylation, immune interactions, and associations with proliferation and metastasis‐related genes using publicly available datasets." (PMID 40548474, 2025). "Previous studies have highlighted roles for C1GALT1 in cancer development and/or progression through diverse mechanisms." (PMID 39894896, 2025). "In this study, we aimed to evaluate the role of T‐synthase in cancer pathogenesis by comparing C1GalT1 gene expression levels in healthy and malignant tissues across a spectrum of cancer types by using bioinformatic tools and the TCGA cancer database." (PMID 40548474, 2025). "This study evaluates the expression, regulation, and clinical relevance of C1GALT1, a key enzyme in mucin‐type O‐glycosylation, across a broad spectrum of human cancers." (PMID 40548474, 2025). "The expression levels of the C1GalT1 gene (median FPKM) in different cancer types were compared using the HPA database." (PMID 40548474, 2025). "This study comprehensively analyzed the expression patterns, clinical correlations, and potential biological significance of the C1GALT1 gene across a wide range of cancer types using publicly available datasets and bioinformatics platforms." (PMID 40548474, 2025). "The correlation between the C1GalT1 gene expression and proliferation‐related genes in various cancer types." (PMID 40548474, 2025). "This study aims to computationally investigate C1GALT1 expression, regulation, and clinical relevance across multiple cancers using TCGA datasets to evaluate its potential as a biomarker and therapeutic target." (PMID 40548474, 2025). "Among the proliferation‐associated genes analyzed—including MKI67, PCNA, MCM2–7, MAP17 (PDZK1IP1), and PLK1—many demonstrated strong positive correlations with C1GALT1 expression in cancers such as pancreas, bladder, breast, stomach, prostate, and liver." (PMID 40548474, 2025). "Median C1GalT1 gene expression differences between metastatic (M1) and non‐metastatic (M0) tissues across different cancer types." (PMID 40548474, 2025). "The correlations between C1GALT1 expression and both Tregs and MDSCs within the same cancer types were found to be parallel across all analyzed cancer types." (PMID 40548474, 2025).
cancer (continued). "The C1GalT1 mean RNA expression levels based on metastatic status were compared in log2 fold change using the Xena web portal using the TCGA cancer datasets." (PMID 40548474, 2025). "This bioinformatic analysis highlights the complex role of C1GALT1 in cancer, showing its differential expression, epigenetic regulation, and associations with prognosis, proliferation, metastasis, and immune modulation." (PMID 40548474, 2025). "This contrasting behavior underscores the complex and variable impact of C1GALT1 on the immune microenvironment across different cancer types." (PMID 40548474, 2025). "Pan-cancer analysis revealed that C1GALT1 exhibited a positive correlation with most of functional states in LUAD." (PMID 38662050, 2024). "In most other cancers, aberrantly high expression of C1GALT1 has been found, and it is generally considered an oncogene." (PMID 38662050, 2024). "Other studies also demonstrated that C1GALT1 was used to as a biomarker to identify different cancers." (PMID 38845937, 2024). "At present, the role of C1GALT1 can be complex and context-dependent, leading to differing effects observed in various studies and cancer types." (PMID 38662050, 2024). "There are several validated mechanisms of C1GALT1 contributing to aggressive cancer behaviors including radioresistance." (PMID 38662050, 2024). "The mRNA expression profile of C1GALT1 showed high expression in 16 TC cell lines from the Cancer Cell Line Encyclopedia (CCLE) database." (PMID 38845937, 2024). "Recent research has unveiled that knockout of the Zn2+-transporter SLC39A9 (ZIP9), alongside the well-described targets C1GALT1 (C1GalT1) and its molecular chaperone, C1GALT1C1 (COSMC), results in surface-expression of cancer-associated O-glycans." (PMID 38699634, 2024). "Studies shown that C1GALT1 is abnormally expressed in a variety of malignant tumors, such as colorectal cancer, gastric cancer, pancreatic adenocarcinoma and lung cancer." (PMID 38845937, 2024). "A number of cell membrane proteins such as N-myristoyltransferase 1 (NMT 1), CD71, Ep-CAM and MIF are seen to be extracted by MGL differentially from C1GalT1-expressing and knockdown cancer cells in this study." (PMID 37612278, 2023). "This indicates that suppression of C1GalT1 in cancer cells substantially reduced galectin-3 binding to its cell membrane receptors." (PMID 37612278, 2023). "Over expression of C1GalT1 correlates with high malignancy, poor prognosis and poor survival of cancer patients." (PMID 37612278, 2023). "A loss of C1GALT1 resulted in a Tn enrichment on CD44, which activated ERK/NF-κB signaling and facilitated the cancer stem cell features in pancreatic cancer cells." (PMID 35864552, 2022). "Core 1 β1,3-galactosyltransferase (C1GALT1) controls the crucial step of GalNAc-type O-glycosylation, and its altered expression affects cancer behaviors." (PMID 35169131, 2022). "Dysregulation of C1GALT1 is involved in cancer development and progression by promoting either O-glycan truncation or elongation." (PMID 36553184, 2022). "We have identified that multiple RTKs, such as EGFR, FGFR2, EPHA2, and MET, are key targets for C1GALT1 and their appropriate O-glycosylation is essential for cancer progression and metastasis." (PMID 35169131, 2022). "C1GALT1 is commonly upregulated during tumorigenesis, including development of hepatocellular carcinoma, breast cancer, and some other types of cancer." (PMID 35864552, 2022). "Truncated O-glycans and responsible enzyme C1GALT1 play important roles in a variety of physiological and pathological processes, including cancer development and progression." (PMID 35864552, 2022). "Silencing C1GALT1 expression inhibits cancer progression by blocking O-glycan elongation on several growth receptors—e.g., EGFR, MET receptor, FGFR2, β1-integrin." (PMID 35207462, 2022). "Taken together, dysregulation of C1GALT1 is involved in cancer development and progression by promoting either O-glycan truncation or elongation." (PMID 35207462, 2022).